AR (androgen receptor)
Diseases named in the same sentence as AR in open-access papers (continued):
Sharing a sentence is not in itself a finding about the gene and the disease.
tumor (continued). "The possible mechanisms include the high expression of androgen receptor in male PTC tissues and the promotion of tumor cell invasion through MAPK/ERK pathway." (PMID 40469187, 2025). "We found that AR inhibition decreased ER-mutant BC adherent and anchorage-independent cell proliferation under LTED conditions, supporting a general pro-tumor role for AR in this therapeutic context." (PMID 41216931, 2025). "Overall, our immunostaining data support the conclusion that matrix stiffness plays a dominant role in regulating GBM cell function, particularly AR and HSP27 expression, with softer environments promoting more biomimetic tumor phenotypes." (PMID 40572374, 2025). "In VETC+ (vascular encapsulated tumor cluster‐positive) HCC cells, AR overexpression inhibits VETC formation and intrahepatic metastasis." (PMID 40583627, 2025). "For instance, androgen deprivation therapies (ADTs), which reduce androgen levels or prevent AR role, have been reported to reduce ERG expression in TMPRSS2:ERG fusion-positive tumours, thus reducing their oncogenic potential." (PMID 40165885, 2025). "This work also identified that AR promotes OXPHOS and FAO, which are facets of tumor metabolism recently demonstrated to be critical to anti-estrogen/AI-resistant BC." (PMID 41216931, 2025). "The Lehmann classification has been reviewed after a better understanding of the immune-related tumor microenvironment and now includes the Basal-Like 1 and 2 (BSL 1 and 2), Mesenchymal (M), and Luminal Androgen Receptor (LAR) subtypes." (PMID 40002228, 2025). "The AR signaling pathway also exhibits significant cross-talk with the PI3K/Akt and MAPK pathways, creating a complex regulatory network that influences tumor biology." (PMID 39757310, 2025). "Clinically, ERG+/PTEN+ tumours are known to be sensitive to AR-targeted therapies, such as androgen deprivation therapy (ADT), abiraterone, and enzalutamide, which form the keystone of treatment for this tumour molecular subtype." (PMID 40165885, 2025). "NRG1 can bind HER3 on tumor cells and promote HER2/HER3 signaling, engaging survival pathways such as PI3K–AKT under AR inhibition and thereby sustaining survival and fostering resistance to antiandrogen therapy." (PMID 41514658, 2025). "Specifically, we seek to clarify how AR and TAN expression patterns correlate with tumor invasiveness, differentiation, and other tumor biomarkers." (PMID 40734715, 2025). "The most contrasting metastasis subtypes, MetA and MetB, can be identified using two immunohistochemical markers: Ki67 for tumor cell proliferation and PSA for luminal cell differentiation and androgen receptor (AR) activity." (PMID 40841830, 2025). "Immunohistochemistry (IHC) staining and western blotting of tumor xenografts 5 days post treatment confirmed significant downregulation of p300/CBP, AR, PSA, MYC, Ki67, CCND1, NKX3-1, CITED2, H3K27ac and H2BK20ac." (PMID 41044247, 2025). "The ROR2–ASCL1 axis is validated as a molecular circuit where therapeutic pressure suppresses AR signaling, leading to ROR2 induction and downstream ASCL1-mediated reprogramming of the tumor lineage." (PMID 41470892, 2025). "By lowering testosterone, AR (androgen receptor) stimulation is diminished, which in turn reduces PSA (prostate-specific antigen) levels and halts tumor growth." (PMID 40868127, 2025). "For instance, significant tumor regression was observed when combining PI3K and AR pathway inhibitors in preclinical PCa models." (PMID 40427108, 2025). "Recent studies have put this AR heterogeneity in the context of tumor response to ADT/ARPIs and other therapies—although the AR+ PCa responds to enzalutamide, AR−/lo PCa and CRPC are inherently resistant to ARPIs." (PMID 41315064, 2025). "Therapeutically, AR-targeted treatments, such as abiraterone, enzalutamide, and androgen deprivation therapy (ADT), are efficient against ERG-driven tumours." (PMID 40165885, 2025).
tumor (continued). "We developed an AR-positive, ENZ-resistant PDX subline from a CRPC model LuCaP35CR through treatment of the tumor-carrying mice with 20 mg/kg ENZ (p. o)." (PMID 40370549, 2025). "To explore the role of SOX2-OT in AR-induced TNBC tumorigenesis, we treated MDA-MB-231 and Hs578t cells with shSOX2-OT and/or DHT and detected the changes of tumor cell biological characteristics." (PMID 40118451, 2025). "In summary, the inhibition of Stat5 by IST5-002 reduced AR-FL and AR-V mRNA levels in both androgen-sensitive and castrate-resistant CWR22Pc tumors, which was accompanied by decreased CRPC tumor growth." (PMID 38416822, 2024). "Through the use of immunohistochemistry, tumor cells have been shown to express CD10, ER, PR, and androgen receptor (AR) in 71–93%, 71–95%, and 59–73% of instances, respectively." (PMID 39064514, 2024). "In AR-transfected HEC50B cells, DHT induced a significant decrease in cell proliferation, wound healing, colony formation, and tumor formation, indicating that androgen suppresses the progression of endometrioid cancer cells in vitro." (PMID 38890503, 2024). "The inflammatory cytokine IL-23 produced by MDSC has been recently linked to CRPC development, since it induces the transcription of AR target genes through STAT3 transcription factor, leading to the proliferation of cancer cells and tumor survival." (PMID 39635522, 2024). "By re-challenging the tumor cell, BAT has demonstrated the capacity to resensitize patients to earlier innovative AR-targeted medicines, such as abiraterone and enzalutamide." (PMID 39351434, 2024). "This hindered transcription factor access and downstream activation of the oncogenic transcriptional programs regulated by AR, FOXA1, ERG, and MYC and led to inhibition of CRPC tumor growth." (PMID 38586029, 2024). "Supporting our STRING analysis, a study of the AR interactome showed that PELP-1 and β-catenin were significantly upregulated in PCa tumour compared to normal tissue." (PMID 39671399, 2024). "It was suggested that miRNA-145 acts as a tumor suppressor by suppressing the expression of HIF-2α and VEGF, as well as upregulating AR-suppressed miRNA-145, by binding to AREs in the miRNA-145 gene at the promoter region." (PMID 39585048, 2024). "In ER-positive tumors, AR expression is correlated with the small size of the tumor (≤2cm), lower TNM (Tumor, Node, Metastasis) stage, lower histological grade, and better outcome." (PMID 39497884, 2024). "Despite this limited overall difference in the signaling pathways, individual AR-related and NEPC genes were all generally upregulated in the cold tumor." (PMID 38253539, 2024). "In in vitro studies, the antioxidant N-acetyl cysteine reduced AR expression, and along with ADT, it decreased xenograft tumor growth in androgen-responsive LNCaP and 22Rv1 cells." (PMID 39000269, 2024). "PDIA5 is also involved in several tumor-related regulatory pathways to influence tumor progression, such as the PI3K/AKT, RTK signaling, and androgen receptor signaling pathways 15-17." (PMID 39247813, 2024). "Consistent with our in vitro findings, immunohistochemistry (IHC) staining and western blotting of tumor xenografts five days post treatment confirmed significant downregulation of p300/CBP, AR, PSA, MYC, Ki67, CCND1, NKX3–1, CITED2, H3K27ac, and H2BK20ac." (PMID 38586029, 2024). "On the other hand, in the OE-AR-ASS1P3 model, it seems that the AR blocked ASS1P3’s sponging ability, allowing miR-34a-5p interaction and the inhibition of ASS1, therefore increasing tumor growth." (PMID 39585048, 2024). "Thus, USP54 may affect CRPC AR signaling activity, which influences tumor growth." (PMID 38321455, 2024). "Although CRPC usually emerges following AR‐targeted therapies, including ADT and ARPIs, the majority of CRPC tumours still rely on an enhanced AR protein level or signalling." (PMID 38214432, 2024).
tumor (continued). "Enzalutamide, an AR antagonist approved for treatment of CRPC, induced moderate tumor growth inhibition, as previously reported in this model." (PMID 38557192, 2024). "Immunohistochemistry (IHC) staining of these tumor samples showed a significant reduction of UBE2J1, accompanied by an increase in AR and AR target NKX3.1 proteins, in PCa compared to matched benign prostate tissue." (PMID 38030789, 2024). "Studies have demonstrated that AR is expressed in up to 50% of TNBC cases, and its inhibition has been shown to decrease cancer stem cell populations and tumor initiation, suggesting a potential target for overcoming resistance to chemotherapy." (PMID 38918989, 2024). "Moreover, androgen receptor signaling may suppress anti-tumor immunity." (PMID 38398136, 2024). "Interestingly, HOXC8 may promote tumor cell invasiveness when AR activity is down-regulated." (PMID 38104650, 2024). "Consistent with their well-differentiated glandular morphology, RPM-Ascl1KO tumors were dominated by AR+;KRT8+ tumor cells." (PMID 39394434, 2024). "Metformin increases STAT3 in advanced PCa cases, leading to significant tumor growth attenuation, underscored by reduced mTORC1/CREB and AR levels in a PCa murine model." (PMID 38811984, 2024). "Our findings shed light on the genome-wide network of OCT1 and AR in AR-positive CRPC and highlight the potential role of CTBP2 in immune response and tumor progression." (PMID 38698344, 2024). "AR indifference represents an adaptive response to androgen deprivation therapy (ADT), driven by epithelial plasticity, an inherent ability of tumor cells to adapt to their environment by changing their phenotypic characteristics in a bi-directional way." (PMID 38398199, 2024). "This article provides a comprehensive overview of the interplay between the AR and ncRNAs in the progression of RCC, with them being involved in regulating tumor initiation, proliferation, invasion, and metastasis." (PMID 39585048, 2024). "On another note, a positive correlation was reported between heightened AR levels and increased expression of the VHL tumor suppressor, hinting at an alternative mediator through which AR acts." (PMID 39585048, 2024). "This is supported by the positive correlation between the expression levels of AR, CDH2, PRKAA1 and tumor purity." (PMID 39342345, 2024). "For example, AR gene suppression in PCa models (e.g., DU145 and LNCaP) increases self-renewal capacity and significantly upregulates relevant tumor stem cell markers, such as CD44, SOX2, and acetaldehyde dehydrogenase (ALDH)." (PMID 39092186, 2024). "To further elucidate the relationship of AR and BCL2 expression, we studied CP336, a PDX with 2 tumor cell populations: AR-positive/BCL2-negative and AR-negative/BCL2-positive." (PMID 39286979, 2024). "Mechanistically, in PCa the AR regulates target genes that control cell cycle such as SPOP or LRIG or interacts with tumor suppressors." (PMID 38902772, 2024). "The G3BP1-SPOP bound ubiquitin activates AR signalling and upregulates G3BP1 transcription, leading to overexpression of G3BP1 in PCa tumour cells and further inhabitation of the tumour suppressor SPOP." (PMID 37749167, 2024). "Other studies have also shown that PDIA5 can regulate tumor progression by participating in multiple signaling pathways, such as the PI3K/AKT, the RTK, and the androgen receptor signaling pathways 38-40." (PMID 39247813, 2024). "Stat5 inhibitor, IST5-002, at nanomolar concentrations suppresses AR levels and PC growth in experimental PC models, including CRPC cells, CRPC tumors, and patient-derived PCs cultured ex vivo in tumor explant cultures." (PMID 38416822, 2024). "The presented case had AR amplification and SCC component of the tumor—both predictive of poor response to ARPI." (PMID 38785459, 2024).
tumor (continued). "A detailed histopathological review and immunohistopathological staining for ER, PR, HER2/neu, AR, EGFR, and Ki-67 were performed on formalin-fixed paraffin-embedded (FFPE) tumor tissue blocks." (PMID 39439618, 2024). "Emerging studies indicate that AR is overexpressed in TNBC,33, 36 and its expression levels correlate with tumor size, lymph node metastasis, and high‐grade tumors in patients with TNBC." (PMID 37903548, 2024). "In addition, another histone lysine demethylase, KDM5D, has been shown to act as a tumor suppressor by physically interacting with AR in the nucleus and regulating its transcriptional activity by demethylating H3K4me3 active transcription marks, to suppress AR signaling." (PMID 38254784, 2024). "The results suggested that downregulation of tumor suppressive miR-99b-5p mediates the upregulation of the mTOR/AR/SMARCD1 signaling axis, consequently promoting tumor aggressiveness and metabolic reprogramming in AA PCa and CRPC." (PMID 38256166, 2024). "It was confirmed that intratumoral steroidogenesis is a significant source of androgens in AR-positive RCC, that AA contributes to significant tumor suppression, and that the androgen signaling axis is a potential target for intervention in RCC." (PMID 39598525, 2024). "We aimed to identify the alteration status in key genes involved in AR signaling, apoptosis, DNA damage repair, and PI3K/AKT/PTEN, in addition to tumor-suppressing genes." (PMID 38892296, 2024). "In transcriptomic data from 138 CRPC tumours, levels of ST3GAL1 gene expression were negatively correlated with AR, KLK3, NKX3." (PMID 38448753, 2024). "Immunohistochemically, the tumours are positive for PSA, AR, ChromograninA or Synatophysin and have a high Ki67 index (median 50%)." (PMID 38374116, 2024). "A benefit has also been shown in a combination of AR targeting with radiotherapy in AR+ TNBC, where AR modulation was used not only as a targeted therapy but also as a radio-sensitizing drug, leading to an amplified response of the tumor to radiotherapy." (PMID 39399414, 2024). "Tumor cells downregulated androgen receptor (AR) expression and induced CAF biomarkers in stromal fibroblasts.Both tumor cells and stromal CAFs migrated through the 8 μm pore size membrane and into their neighboring channel." (PMID 39459070, 2024). "Tumor-bearing mice treated with Bm@PT/Enz-miR26a showed significant fluorescence of SFRP1 and decreased fluorescence of EZH2, WNT5A, and AR compared to other groups." (PMID 38566211, 2024). "Our study found that KHSRP acetylation as a downstream regulator of AR can widely promote the expression of DDR‐related genes, especially the AREs‐containing genes, to drive tumor growth in PCa." (PMID 38501452, 2024). "To assess the expression of AR and PSMA in tumor tissue following treatment with Abi, Chl, and their combination, we performed immunofluorescent staining and quantitative automated immunoblotting." (PMID 39409882, 2024). "Taken together, these results suggest that AR plays a critical role in the cellular interplay and stochastic interactions in the TME that influence tumor cell behavior and CRPC development." (PMID 38383542, 2024). "Comprehensive genetic profiling, using institutional tumor next-generation sequencing panel Genetrails, of the pretreatment prostate biopsy showed genomic alterations in PIK3CA p.E542K, MUTYH p.G393D and androgen receptor (AR) amplification (11 copies)." (PMID 38785459, 2024).
tumor (continued). "The data provide evidence of the tumor suppressive activity of SAL and a novel signaling by the AR-BHLHE40-CCNG2 axis for androgen-induced cellular senescence, linking circadian rhythm factor to androgen signaling as a novel tumor suppressive pathway." (PMID 38902772, 2024). "In addition to normal tissues and tumor cells, ARs are also expressed on the surface of various immune cells that include neutrophils, monocytes, natural killer (NK) cells, macrophages, and mature dendritic cells, in which the ß2-AR is the most highly expressed AR subtype." (PMID 36835082, 2023). "Elevated expression levels of HOXB13 have been shown in CRPC tumours when compared to hormone-sensitive tumours, and it has been demonstrated that HOXB13 interacts with the DBD of the AR, regulating the transcriptional activity of genes containing AREs." (PMID 36937454, 2023). "On the other hand, by lowering cholesterol levels, statins reduce lipid rafts, affecting the epidermal growth factor receptor, the androgen receptor and the AKT and JAK-SATA three pathways, thus suppressing the growth of tumor cells." (PMID 37297021, 2023). "In agreement with our studies, previous work from other labs demonstrated cisplatin mediated up-regulation of NK cell cytotoxicity through suppression of AR, and upregulation of ULBP-2 in the HCC tumor model." (PMID 37197660, 2023). "CBP/p300 are potent coactivators of the AR, and perturbation of p300/CBP function in PC models decreases AR function and reduces tumor cell growth." (PMID 37477521, 2023). "We find that metformin treatment of STAT3/AR-expressing PCa xenografts resulted in significantly reduced tumor growth accompanied by diminished mTORC1/CREB, AR and PSA levels." (PMID 37573301, 2023). "While PSA is a direct downstream target of the activated AR, a lower level of PSA is present in these advanced tumor types." (PMID 36765916, 2023). "MTX-23 is capable of degrading both AR-FL and AR-V7, and shows potent inhibition of CRPC tumor growth with combined use of enzalutamide." (PMID 36893587, 2023). "In most cases, PCa is an AR-dependent tumor; thus, androgen deprivation therapy (ADT) and AR signaling inhibition (ARSI) therapy persist as the mainstay systemic therapies for patients with recurrent or metastatic PCa." (PMID 37686633, 2023). "We also found that in both adenocarcinoma tumor cells and PDX models, NK1R expression was inducible with AR inhibitor or castration treatment." (PMID 37385990, 2023). "ERα and AR proteins also correlated positively, whereas ERβ and PGR inversely, with tumor characteristics." (PMID 37206439, 2023). "Our work highlights a systemic impact of ADT on TAMs of PCa and reveals a key cytokine that is directly regulated by the AR pathway in TAMs, which provides new insight into our understanding how ADT affects immune cells in the tumor microenvironment." (PMID 37092583, 2023). "N-Myc increases the stability of AURKA by blocking its association with the E3 ubiquitin ligase FBXW7 and binds to the promoters of target genes such as NSE, Syn, and AR to control their expression, ultimately resulting in NEPC tumor progression." (PMID 36678591, 2023). "AR knockdown statistically significantly decreased FEN1, pho‐ERK1/2 and pho‐ELK1 expression in tumour tissues of nude mice as compared with the 22Rv1‐control group (all p < 0.001)." (PMID 37326412, 2023). "BET inhibition using compound JQ1 disrupts the recruitment of AR to target gene sites BET inhibition blocks E2F1/BRD4-regulated program and decreases growth of NEPC tumor models." (PMID 36711033, 2023). "In a deeper examination of the tumor tissue, we observed a considerable decrease in the mRNA expression levels of PSA and KLK2 - known target genes of AR - in response to the combined therapy of YIV-818-A and enzalutamide." (PMID 37860121, 2023).